CEACAM5 (CEA cell adhesion molecule 5)
Diseases named in the same sentence as CEACAM5 in open-access papers (continued):
Sharing a sentence is not in itself a finding about the gene and the disease.
pancreatic cancer (continued). "Targeting CEACAM5 is under investigation in gastrointestinal cancer, and its role in pancreatic cancer remains unclear." (PMID 39410042, 2024). "CEACAM5 has previously been linked to NEPC and has been shown to be an effective target for killing NEPC cells as well as other cancer types such as colorectal and pancreatic cancer." (PMID 37546702, 2023). "Therefore, uncovering stemness-high pancreatic cancers with high CEACAM5 expression increase the possibility of applying immunotherapy for the clearance of pancreatic cancer stem cells." (PMID 36494785, 2022). "CAR-T cells targeting carcinoembryonic antigen-related cell adhesion molecule 5 (CEACAM5) used for the treatment of breast, gastric, colorectal, lung, ovarian, and pancreatic cancers induced acute respiratory toxicity, likely due to CEACAM5 expression on non-neoplastic lung epithelium." (PMID 36531912, 2022). "Our study reveals CEACAM5 as a stemness-related inhibitory immune checkpoint in pancreatic cancer." (PMID 36494785, 2022). "As heterogeneity also exists in cancer stem cells, we wondered whether different subpopulations of pancreatic cancer stem cells exhibit distinct inhibitory immune checkpoints except for CEACAM5." (PMID 36494785, 2022). "It is reasonable to infer that proliferating CEACAM5+ pancreatic cancer stem cells may act as deadly seeds in recurrence and that detection of those cells could be an approach to determining metastatic burden." (PMID 36494785, 2022). "Our study revealed that long-chain unsaturated fatty acids may regulate CEACAM5 expression and that proliferating stemness-high pancreatic cancers with high CEACAM5 expression may adopt a dual phenotype of oxidative phosphorylation and fatty acid oxidation." (PMID 36494785, 2022). "Notably, CEACAM1, CEACAM5, and CEACAM6 have been found to be implicated in immune related disease and cancer, and are now considered valid clinical biomarkers and promising therapeutic targets in melanoma, lung, colorectal, and pancreatic cancers." (PMID 36741860, 2023). "Our study indicated that the infiltration of M1 macrophages and neutrophils in pancreatic cancer can signify prolonged patient survival and that CEACAM5 in stemness-high pancreatic cancers could impair the tumoricidal function of M1 macrophages and neutrophils." (PMID 36494785, 2022). "Therefore, blockade of IFN-γ signalling or those metabolic processes, and application of those small inhibitors may synergize with anti-CEACAM5 antibodies to improve the elimination of immune evasion in stemness-high pancreatic cancers." (PMID 36494785, 2022). "The pancreatic cancer cell lines with higher levels of CEACAM5 generated fewer ATPs when exposed to niclosamide, palmostatin, SB-225002, SGX-523, axitinib, SCH-79797, sorafenib and 3-CI-AHPC, which means that those inhibitors could efficiently target CEACAM5high pancreatic cancer cells." (PMID 36494785, 2022). "Meanwhile, those three metabolic processes were found associated with CEACAM5 expression as expected, suggesting prostanoid and long-chain unsaturated fatty acid metabolic processes could regulate CEACAM5 expression to influence the immune evasion of stemness-high pancreatic cancers." (PMID 36494785, 2022). "Thus, stemness-high pancreatic cancers may impair innate immunity such as macrophage through the expression of CEACAM5." (PMID 36494785, 2022). "Although CEACAM1 was not proven highly expressed in the high mRNAsi score group, or closely correlated with ICS and MTS, it can be inferred that CEACAM1+ CEACAM5+ cancer cells may be a small subpopulation of CEACAM5+ pancreatic cancer stem cells endowed with an elevated immune privilege." (PMID 36494785, 2022). "Synergistic inhibition of stemness-related regulatory metabolisms, including prostanoid and long-chain unsaturated fatty acid metabolic processes, may improve the efficacy of ICB treatment which is aimed at eliminating immune evasion in stemness-high pancreatic cancers with high CEACAM5 expression." (PMID 36494785, 2022).
pancreatic cancer (continued). "Thus, targeting CEACAM5 with ICP blockers could enhance pancreatic cancer therapy efficacy." (PMID 41233805, 2025). "Consistently, a bioinformatics analysis of pancreatic cancer-specific datasets from TCGA and the Cancer Therapeutics Response Portal (CTRP) identified CEACAM5 as a candidate stemness-related inhibitory ICP in pancreatic cancer." (PMID 41233805, 2025). "Among the nineteen UDEGs, other than the seven UDEGs reported to be carcinogenic and prometastatic genes involved in pancreatic cancer, the other UDEGs, such as ESM1, PCDH7, CORO2A, CEACAM5, GALNT5 and TMPRSS4, are also involved in other cancers." (PMID 40362181, 2025). "Among them, pancreatic cancer cells in the cluster 8 with TIMP1+/FN1+ showed the strongest resistance, while the cluster 1 with CLDN18-/CEACAM5- and the cluster 7 with HSPA6+/NEAT1+ showed milder resistance." (PMID 38343537, 2024). "Similar to CEACAM5, CEACAM6 overexpression was considered a potential driving force of pancreatic cancer progression." (PMID 34663338, 2021). "CEACAM5, also called CEA (carcinoembryonic antigen), is a major marker of progression and metastasis in digestive malignancies such as colorectal and pancreatic cancers." (PMID 34663338, 2021). "Altered N-glycosylation in pancreatic cancer tissue compared to normal pancreatic tissue was reported for MUC5AC, LGALS3BP, CEACAM5, and IGFBP3." (PMID 30771135, 2019). "Currently, CEACAM1, CEACAM5, and CEACAM6 are considered as valid prognostic markers and promising therapeutic targets in melanoma, lung, colorectal, and pancreatic cancers." (PMID 29137373, 2017). "Both models exhibit comparable and high CEACAM5 expression and low CD3 T cell infiltration at baseline, making them xenograft models with good translational potential for colorectal, gastric and pancreatic cancers." (PMID 41283511, 2025). "Besides CEA, several other glycoproteins of the carcinoembryonic antigen-related cell adhesion molecule (CEACAM) family are emerging as cancer biomarkers, such as CEACAM1, CEACAM5 (synonym of CEA) and CEACAM6 for pancreatic cancer." (PMID 38515194, 2024). "This study presented a set of glycoproteins having aberrant N-glycosylation levels in pancreatic cancer, including mucin-5AC (MUC5AC), carcinoembryonic antigen-related cell adhesion molecule 5 (CEACAM5), insulin-like growth factor binding protein (IGFBP3), and galectin-3-binding protein (LGALS3BP)." (PMID 33672926, 2021). "Interestingly N-glycosilation levels were increased in pancreatic cancer samples,] from proteins such as mucin-5AC (MUC5AC), carcinoembryonic antigen-related cell adhesion molecule 5 (CEACAM5), insulin-like growth factor binding protein 3 (IGFBP3) and galectin-3 binding protein (LGALS3BP)." (PMID 31349663, 2019).
lymph node metastasis (67 papers, 2005 to 2025). "CEACAM5 levels have been suggested to serve as prognostic determinants and have been correlated with metastatic lymph node tumor burden." (PMID 36397035, 2022). "Work by Shousha and colleagues showed that expression of CEACAM5 in primary carcinomas correlated with lymph node metastases and with lower patient survival rates." (PMID 33196697, 2020).
ovarian carcinoma (58 papers, 1976 to 2026). A malignant neoplasm originating from the surface ovarian epithelium. "TATs highly expressed in cervical cancer include CEACAM5, CD71, CD138, FGFR3, LYPD3, CEACAM6, etc.; VEGF is also highly expressed in ovarian cancer; CD71 and CD138 are highly expressed in endometrial cancer; the TATs highly expressed in uterine sarcoma include B7-H3, DLK1, and EFNA4." (PMID 40046734, 2025). "In contrast to the chemerin protein data from IHC, mRNA levels of the RARRES2 gene in ovarian cancer were not correlated with PGR, ESR2, ESRRA, ESRRB, ESRRG, nor CEACAM5 after analysis of both patient collectives on the mentioned platforms (p > 0.05 for all)." (PMID 36900088, 2023). "Two well-studied TAAs for PDAC and ovarian cancer, MUC16, and CEACAM5, illustrate the two principal challenges of targeting non-mutated TAAs: difficulty in breaking T-cell tolerance and, conversely, the potential for induction of on-target off-tumor toxicities." (PMID 33087697, 2020).
non-small cell lung carcinoma (55 papers, 1995 to 2026). A group of at least three distinct histological types of lung cancer, including non-small cell squamous cell carcinoma, adenocarcinoma, and large cell carcinoma. "High expression of CEACAM5 is associated with worse survival in patients with non-small cell lung cancer." (PMID 39796075, 2024). "Many breast, pancreatic, colonic and non-small-cell lung carcinoma lines express CEACAM6 (NCA-90) and CEACAM5 (carcinoembryonic antigen, CEA), and antibodies to both can affect tumor cell growth in vitro and in vivo." (PMID 17201906, 2007).
squamous cell carcinoma (50 papers, 2007 to 2025). A carcinoma arising from squamous epithelial cells. "Exceptions (phet < 0.05) included CEACAM5, which was more strongly associated with adenocarcinoma than squamous cell carcinoma, and MMP12, which was more strongly associated with squamous cell carcinoma than with adenocarcinoma." (PMID 37264016, 2023). "Squamous cell carcinomas seemed to have high levels of both these marker groups, but not of CEACAM5 mRNA." (PMID 23671585, 2013).
cyst (42 papers, 2009 to 2025). A sac-like closed membranous structure that may be empty or contain fluid or amorphous material. "Such comparison resulted in 4 upregulated (CP, CEACAM5, DMBT1, and KRT6A) and 8 downregulated (CEL, CPA1, CPB1, ALB, SERPINA4, CA2, CLU, and AMBP) DEGs secreted in cyst fluid of high-risk IPMNs." (PMID 34790815, 2021). "In the current study population, we did not perform cyst fluid analysis via EUS-FNA, which permits not only pathological examinations but also molecular profiling based on genomic annotations and specific molecules (e.g., CEACAM5 [CEA], glucose)." (PMID 37507590, 2023).
lung adenocarcinoma (38 papers, 2007 to 2026). A carcinoma that arises from the lung and is characterized by the presence of malignant glandular epithelial cells. "Second, we assessed glycoprotein expression levels in 33 patients diagnosed with lung adenocarcinoma from our institution to assess local rates of CEACAM5 tumor presence." (PMID 36705924, 2023). "Although other CEACAM family proteins, such as CEACAM1 and CEACAM5, are known to be dysregulated in lung adenocarcinoma as well, CEACAM6 is more highly expressed than CEACAM5 and is associated with poor clinical outcomes among lung adenocarcinoma patients." (PMID 31474761, 2019). "CD40 and CEACAM5 were the top DCGs in the lung adenocarcinoma group, and both play important roles in cancer biology." (PMID 26029238, 2015). "CEACAM5 is highly expressed in approximately 20% of patients with lung adenocarcinoma." (PMID 41266534, 2025). "To validate our CEACAM5 observations, we obtained batch corrected RNA-seq data from The Cancer Genome Atlas Pan-Cancer Initiative for primary and metastatic/recurrent lung adenocarcinoma, breast invasive carcinoma, and pancreatic adenocarcinoma tumors, as well as normal tissues." (PMID 33004987, 2020). "CEACAM5 expression was significantly higher in primary lung adenocarcinoma (p = 1.5e−14), primary breast invasive carcinoma (p = 2.1e−11), and primary pancreatic adenocarcinoma (p = 3.0e−6) when compared to normal lung, breast, and pancreatic tissues, respectively, adjusting for age and sex." (PMID 33004987, 2020). "The prescreening strategy using CEACAM5 and HMGB3 expression facilitates tumor-centric scRNA-seq analyses of lung adenocarcinoma." (PMID 36397035, 2022). "We found that CEA cell adhesion molecule 5 (CEACAM5) and high mobility group box 3 (HMGB3) were reliable markers for RT-PCR-based prescreening of tumor cells in lung adenocarcinoma." (PMID 36397035, 2022). "Altogether, these results suggest that real-time PCR screening of CEACAM5 and HMGB3 can be used to confirm the presence of tumor cells in lung adenocarcinoma specimens of both tissue and lymph node origin, as well as in cDNAs and single-cell or nuclear RNA sequencing libraries." (PMID 36397035, 2022).
metastatic disease (26 papers, 2010 to 2025). "For 20 of these tumors the expression pattern of CEACAM5 in the primary tumor was in the same category as the corresponding metastatic tumor." (PMID 33196697, 2020). "Identifying molecules that promote macrometastasis, such as CEACAM5, is expected to lead to the development of new therapeutic targets and the application of existing therapies for patients with advanced metastatic disease." (PMID 29736411, 2018). "Human CAR-M cells armed with receptors recognizing CD19, CD22, the carcinoembryonic antigen-related cell adhesion molecule 5 (CEACAM5), CD514, and HER2, have been developed to target primary and metastatic tumors, mediate phagocytosis, and stably express M1 functions." (PMID 37509382, 2023).
liver cancer (18 papers, 2015 to 2025). An epithelial or non-epithelial malignant neoplasm that arises from the liver. "Interestingly, we found that most of these key node genes play important roles in tumorigenesis (RET, CEACAM5), immune regulation (CTSG, CD79A) and the EMT pathway (COL10A1, COL11A2), suggesting their significant role in the recurrence of liver cancer." (PMID 34956309, 2021).
melanoma (18 papers, 2011 to 2024). A malignant, usually aggressive tumor composed of atypical, neoplastic melanocytes. "In fact, both CEACAM1 and CEACAM5 expressed on melanoma or 721.221 cells suppress NK cell-mediated cytotoxicity against tumor cells by interacting with and activating NK CEACAM1, which is a MHC I-independent inhibitory receptor." (PMID 21731662, 2011).
metastatic colorectal cancer (18 papers, 1975 to 2025). "Labetuzumab govitecan represents an anti-CEACAM5 antibody conjugated to 7-ethyl-10-hydroxycamptothecin (SN-38) tested for its safety and antitumor activity in patients with metastatic colorectal cancer." (PMID 38730739, 2024). "The Phase I clinical trial (PROCEADE-CRC-01) has brought new hope to patients with advanced CRC: the global first anti-CEACAM5 antibody-drug conjugate (ADC) Precem-TcT has demonstrated significant safety and encouraging efficacy in heavily pretreated metastatic colorectal cancer patients." (PMID 41266534, 2025). "Interestingly, in one further lung resection sample (W0094T1PNc) from a patient with metastatic colorectal cancer, there was no qPCR signal at all for CEACAM5 and very low-level staining by the anti-collagen 1(Col-1) antibody." (PMID 28660319, 2017).
cervical carcinoma (16 papers, 2012 to 2025). A carcinoma arising from either the exocervical squamous epithelium or the endocervical glandular epithelium. "In the study of cervical cancer, the expression of CEACAM5 and CEACAM6 was similar in five different histological subtypes, with no significant statistical difference." (PMID 40046734, 2025). "CEACAM5 shows a stable gene expression profile and overall, 68.7% (46/67) of cervical cancer samples are CEACAM-positive with 34.3% (23/67) of cervical cancer samples showing at least moderate or high expression." (PMID 38730739, 2024). "For this panel, only CEACAM5 was significantly different in abundance (p = 0.007) between early stage cervical cancer and healthy epithelium found by LCM and mass spectrometry." (PMID 29719595, 2018). "Similar to the other two potential ADC candidates, CD138 shows a stable gene expression over all stages of cervical cancer with an intermediate strength of gene expression as compared to TROP2 and CEACAM5." (PMID 38730739, 2024). "Currently, several ADC targets exist (TROP2, mesotheline, CEACAM5, DLL3, folate receptor alpha, guanylatcyclase, glycoprotein NMB, CD56, CD70 and CD138) with ADC compounds being tested in other cancer entities whose expression level in cervical cancer is of clinical interest." (PMID 38730739, 2024).
colorectal tumors (16 papers, 1994 to 2025). "In colorectal tumors matched with normal adjacent tissues, we observed a strong increase in both CEACAM5 and CEACAM6 levels in tumor tissues, compared to normal tissues." (PMID 38502695, 2024).
diabetes (15 papers, 2012 to 2024). "The features highlighted as predictive under these circumstances included important and widely referenced markers which we confirmed as having among the strongest association with PDAC, namely CA19-9, CEACAM5, MUC16 (CA125), THBS2 and diabetes." (PMID 36670203, 2023).
colorectal adenocarcinoma (13 papers, 2006 to 2025). The most common type of colorectal carcinoma. "In the ongoing study, the possibility of mutations in the binding region (Pro–Glu–Leu–Pro–Lys; PELPK) of the CEACAM5 gene in patients with AA or colorectal adenocarcinoma is being explored in a comparative genetic association analysis." (PMID 38456675, 2024). "Preserving the interactions between CEACAM1 and CEACAM5 might be critical in preventing colorectal adenocarcinomas." (PMID 36741860, 2023). "Meanwhile, another study found the relation between expression of CEA (CEACAM5) gene and TGF-β pathway genes (TGFBR1, TGFBR2, and SMAD3) in colorectal adenocarcinoma cells." (PMID 33123542, 2020). "Conversely, in patient 4 with colorectal adenocarcinoma, who never had serum CEA elevation but had strong CEACAM5 staining at the time of index operation, nodules suggestive of disease were visualized in vivo and ex vivo and were associated with CEACAM5 staining (2+)." (PMID 36705924, 2023).
colitis (12 papers, 2017 to 2025). Inflammation of the colon. "The lack of bowel toxicity in this trial contrasts with the severe colitis seen with T cells armed with TCR specific for CEACAM5." (PMID 28660319, 2017). "By contrast, CEACAM5 transcript is highly expressed in tumors but also in normal colon and esophagus (>300 TPM), leading to severe colitis in patients treated with antigen-specific T cells." (PMID 33087697, 2020). "In addition, AIEC LF82 induced colitis in CEABAC10 transgenic mice harboring human CEACAM3, CEACAM5, CEACAM6, and CEACAM7 genes, and intraperitoneal injection of anti-CEACAM6 significantly decreased LF82 colonization." (PMID 41163391, 2025).
bladder cancer (11 papers, 2007 to 2026). "The binding of mAb CC4 to bladder cancer T2-4 cells transfected with CEACAM5-expressing vectors further validated the recognition of mAb CC4 to CEACAM5." (PMID 21731662, 2011).
pancreatic ductal adenocarcinoma (11 papers, 2012 to 2025). An infiltrating adenocarcinoma that arises from the epithelial cells of the pancreas. "The carcinoembryonic antigen-related cell adhesion molecule 5 (CEACAM5) is overexpressed in tumors including non-small cell lung cancer (NSCLC) and pancreatic ductal adenocarcinoma (PDAC), and is an attractive target for therapies based on CAR-T cell or/and ADCs." (PMID 36923424, 2023).
mucinous adenocarcinoma (10 papers, 2007 to 2026). An invasive adenocarcinoma composed of malignant glandular cells which contain intracytoplasmic mucin. "The highest CEACAM5 expression also was found in the mucinous adenocarcinoma type (1.6 ± 1.5)." (PMID 17201906, 2007).
colon adenocarcinoma (9 papers, 2005 to 2024). "Without additional stratification, there was no emergent association between CEACAM5 or CEACAM6 levels and overall survival or disease-free survival among colon adenocarcinoma patients." (PMID 38502695, 2024). "Much larger amounts of CEACAM6 were found in colon adenocarcinoma (6.2 ± 1.4) compared with non-neoplastic colon (3.0 ± 0.0; P < 0.002) and CEACAM6 expression exceeded CEACAM5 expression (3.4 ± 0.5; P < 0.001)." (PMID 17201906, 2007).
Pancreatic cysts (9 papers, 2013 to 2025). A cyst of the pancreas that possess a lining of mucous epithelium. "For example, the integration of CEA mRNA (CEACAM5) into a combined DNA/RNA NGS platform has been shown to enhance the classification of pancreatic cysts and the detection of high-grade dysplasia and early adenocarcinoma." (PMID 40507590, 2025).